PER2 (period circadian regulator 2)
Diseases named in the same sentence as PER2 in open-access papers (continued):
Sharing a sentence is not in itself a finding about the gene and the disease.
tumor (continued). "Overexpression of the Period 2 (Per2) gene in a tumor-transplant model in animals has been shown to improve the tumor-inhibition rate, as well as inhibit the growth and metastasis of tumor cells." (PMID 33083827, 2020). "PER2 controls circadian rhythm and it has been suggested as a tumor suppressor gene." (PMID 33117405, 2020). "In conclusion, PER2 can serve as a resistance for tumor metastasis in the mouse model." (PMID 32185221, 2020). "The result manifested that Per2 overexpression can restrain tumor growth in vivo." (PMID 32284762, 2020). "Here we show that selective loss of the core clock genes Per1 and Per2 in the TME not only does not promote cancer but actually inhibits tumor growth and metastatic colonization." (PMID 33123539, 2020). "The tumour suppressive properties of PER2 have been previously demonstrated." (PMID 31658284, 2019). "Therefore, when the expression of Bmal1 and Per2 genes is downregulated, tumour cells will grow and proliferate rapidly." (PMID 31744421, 2019). "Downregulation of Per2 is correlated with increased levels of Cyclin D and Cyclin E and accelerated tumor growth in vivo whereas induced overexpression of either Per1 or Per2 has been shown to inhibit the growth of cancer cells and increase their apoptotic rate." (PMID 31409384, 2019). "Restoring PER2 in the tumor cells of a mouse model of sarcoma suppressed tumor growth." (PMID 33089179, 2019). "Tumor cells deficient in per2 were also more proliferative in culture, and mouse embryonic fibroblasts lacking kras and per2 were more sensitive to cellular transformation than their Per2-intact counterparts." (PMID 31773065, 2019). "PER2 deficient mice also had deregulated cell cycle and a lack of tumor suppression, suggesting that PER2 functions to suppress tumors through DNA damage-responsive pathways." (PMID 33089179, 2019). "Per1 negatively affects the growth of tumor cell and per2 functions as tumor repressor." (PMID 29607311, 2018). "Right - normalisation of Per2::Luc activity from normal and tumour MECs." (PMID 30348208, 2018). "In healthy cells, Per2 also may act directly as a tumor-suppressor gene, decreasing the activity of pathways associated with tumor formation." (PMID 28865460, 2017). "Per1 and Per2 have tumor suppression activity, which may tie in with the anti-cancer mechanism under CR." (PMID 28768896, 2017). "The potential involvement of disturbed biological rhythms as causative in cancer is further emphasized by the fact that the expression of two clock genes, Period 1 (Per1) and Period 2 (Per2), are known tumor suppressors in many tissues including the breast epithelium." (PMID 28420185, 2017). "Per2-deficient mice show increased tumor development and Per2 is often elevated in tumor but not in peripheral tissues." (PMID 27036047, 2016). "PER2 has also been found to function as a tumour suppressor, with the absence of both its copies causing an increased rate of radiation-induced cancers." (PMID 27465361, 2016). "Others also propose that Per2 may play important roles in tumor development, invasion and prognosis, and Per2 may serve as a novel prognostic biomarker of human gastric cancer." (PMID 26898709, 2016). "However, if there is decreased expression of both Per1 and Per2 in breast tumours the action of PER as a tumour suppressor becomes reduced." (PMID 27590298, 2016). "Additional lines of evidence, suggest a role for Per2 in tumor suppression." (PMID 27036047, 2016). "In addition, deregulated expression of c-Myc has been suggested as a key factor leading to tumor development in Per2 mutant mice." (PMID 25760074, 2015). "For example, the core clock genes PER1 and PER2 are known tumor suppressor genes, and their knockdown results in the doubling of tumor number and cancer growth; in contrast, overexpression of these genes decreases tumor number and cancer growth." (PMID 26253128, 2015).
tumor (continued). "Also, Per2 plays an important role in setting the period of oscillation and has tumor-suppressor properties." (PMID 25333958, 2014). "PER2 play an important role in tumor suppression and DNA damage response in vivo." (PMID 24708606, 2014). "Later, quite unexpectedly, PER2 was found to function as a tumour suppressor, with the absence of both its copies causing the rate of radiation-induced cancers to rise." (PMID 23303309, 2013). "Furthermore, previous papers indicate that Per2 and C/ebpα have the same effects for tumor suppression events." (PMID 23505471, 2013). "While the circadian genes PER1 and PER2 have been clearly shown to function as tumor suppressors in the mouse model, a recent study showed that epidermal deletion of BMAL1 in a transgenic mouse model which spontaneously develops squamous tumours leads to significantly fewer neoplastic lesions." (PMID 22470559, 2012). "Alternatively, overexpression of Per2 inhibited tumor proliferation in vitro and in vivo." (PMID 22935435, 2012). "Both Per1 and Per2 have been described as tumor suppressor genes." (PMID 21566258, 2011). "All this evidence indicates that Per2 has a role in tumour suppression, but further research is needed to ascertain whether Per2 is in fact a tumour suppressor gene or whether a particular mutation of Per2 acquires oncogenetic properties." (PMID 20353609, 2010). "Irradiated Bmal1+/− mice showed a similar rate of tumor development as did irradiated Per2−/− mice." (PMID 20539819, 2010). "PER2 protein has also been proposed to function as a tumor suppressor." (PMID 20353609, 2010). "Additionally, PER2 acts as a tumor suppressor and is essential in DDR." (PMID 40046513, 2025). "Therefore, PER2 has been hypothesized to function as a tumor suppressor in the liver, acting from hepatocarcinogenesis initiation to progression." (PMID 40521302, 2025). "Hence, we postulated that restoring the expression and oscillation of PER2 induced by metformin could effectively block GBM tumor growth and sensitizes GBM tumors to radiotherapy and or chemo-radiotherapy." (PMID 40166471, 2025). "Mice lacking the PER2 gene are susceptible to cancer and show suppressed tumor growth." (PMID 37069338, 2023). "PER2 may play an essential role in regulating the tumor immune microenvironment." (PMID 38074100, 2023). "In contrast, if the PER2 gene is overexpressed, it may confer tumor-suppressive properties." (PMID 35356228, 2022). "Therefore, KMT2D-mediated Per2 activation represents a previously unknown tumor-suppressive mechanism that links an epigenetic tumor suppressor to a circadian rhythm regulator with direct metabolic implications." (PMID 35071240, 2021). "Additionally, the authors proposed that promoter methylation or cell signaling pathway disruption may influence PER2 expression in tumor tissues." (PMID 34361055, 2021). "Moreover, it has been suggested that PER1 and PER2 function as tumor suppressors." (PMID 30518396, 2018). "However, if effects of melatonin are studied in a poorly or even non-oscillating system such as cancer cells, which may have repressed some oscillator genes with tumor suppressor function, such as Per2, the situation is entirely different." (PMID 25310649, 2014). "Moreover, overexpression of Per2 inhibits tumor proliferation in culture and in animals." (PMID 25333958, 2014).
tumor (continued). "Quite interestingly, recent reports demonstrated that in mammary gland, selenium administration induces upregulation of another circadian protein, PER2, in a BMAL1-independent manner and that this upregulation may underlie tumor preventive properties of selenium compounds." (PMID 22249125, 2011). "In the context of DNA damage, a tumor suppressive function has been suggested for the three PER genes (PER1, PER2, PER3)." (PMID 40352720, 2025). "PER2 expression is decreased in HNSCC tissues, while restoring PER2 expression represses tumor-promoting glycolysis via inactivation several oncogenic glycolytic genes." (PMID 41184251, 2025). "Furthermore, the G allele may influence MT2 expression in breast tissues, leading to changes in the central circadian clock and peripheral oscillators, including the appearance of the clock genes period 1 (Per1) and period 2 (Per2), which are acknowledged as tumor suppressor genes." (PMID 40736027, 2025). "NONO knockdown significantly downregulated the core clock gene PER2 and the oncogene DEC1 and markedly reduced tumor-cell expression of key fibroblast-signal receptors, including ITGB1, SDC1, and CD47." (PMID 41174721, 2025). "PER2 is one of the nine master circadian clock genes located in the SCN and has been suggested as a tumor suppressor." (PMID 40091567, 2025). "The studies published so far showed both oncogenic and tumour suppressor functions of BMAL1, CLOCK, PER1, PER2, PER3, CRY2, and REV-ERBβ." (PMID 38378853, 2024). "As a tumor suppressor gene, KMT2D is known to activate Bcl6 and Sirt1 in addition to Per2, resulting in inhibitory effects on Notch and K-Ras pathways." (PMID 36841815, 2023). "Numerous studies have shown that circadian rhythm regulators, such as PER2, CLOCK, BMAL1, CRY1, and CRY2, act as tumor suppressors in the liver, ovaries, colon, and lung." (PMID 37524704, 2023). "PER2 and PER3 were also founded to be significantly up-regulated in the normal tissue compared to the tumor tissue." (PMID 37968308, 2023). "For example, some studies have shown that PER1 and PER2 are significantly downregulated in OSCC and that their overexpression can inhibit glycolysis and tumor cell proliferation, thus inhibiting tumor growth." (PMID 36566175, 2022). "Unlike the mixed roles of CLOCK and BMAL1 in CSCs, period circadian regulator genes (e.g., PER2 and PER3), generally known as tumor suppressors in various types of cancer, have been shown to inhibit CSC maintenance and survival in tumors." (PMID 36430659, 2022). "Compared to adjacent and benign tissues, tumor tissues from pancreatic ductal adenocarcinoma patients expressed significantly lower levels of circadian clock, including PER-1, PER-2, PER-3, CRY-2, and CK1ε, which are related to poor prognosis." (PMID 33752691, 2021). "We have also shown that expression of the circadian transcription–repressive tumor suppressor Per2 is positively regulated by a KMT2D–activated, tumor-suppressive super-enhancer to attenuate lung tumorigenesis." (PMID 34194626, 2021). "The PER family is generally considered to have a tumor suppressor effect, and the mechanisms behind the tumor suppressing effects of PER1 and PER2 are clear." (PMID 34285836, 2021). "The propagation (metastasis) to distant sites (M) at the moment of the disease diagnosis appeared in tumours with low levels of BMAL1 (p = 0.004) and PER2 (p = 0.037)." (PMID 34440171, 2021). "The expression of CRY2, PER2, PER3 and RORA was correlated with TNM stage, T stage, and tumor differentiation in KIRC patients (p < 0.05)." (PMID 34977153, 2021). "On the contrary, the expression of PER2, PER3, CRY1, KIAA1737, and BHLHE41 are negatively correlated with the infiltration level of four tumor‐infiltrating lymphocytes in pan‐cancer." (PMID 31927791, 2020).
tumor (continued). "Apart from this, recent studies demonstrated that PER2 expression was reduced in OSCC compared with adjacent, non-tumor tissue." (PMID 31151182, 2019). "In addition, the myelocytomatosis oncogene cellular homolog (Myc) proto-oncogene is thought to be regulated by BMAL1/neuronal PAS domain protein 2 (NPAS2) (a CLOCK paralogue) action on its E-boxes, which may contribute to enhanced tumor growth in Per2 mutant mice in response to DNA damage." (PMID 31039152, 2019). "The down-regulation of PER2 in CRC cells increased protein levels of β-catenin and cyclin D, which accelerated tumour cell growth." (PMID 31658284, 2019). "The CCAAT/enhancer binding protein alpha (C/EBPalpha) regulates the expression of PER2 and depletion of BMAL1 in unmethylated cells promotes tumor growth while its reintroduction in tumor cells slowed down growth in colony assays and nude mice." (PMID 28674522, 2017). "Several clock genes showed a down-regulation when compared to their own neighbouring mucosa, i.e. PER1, PER2 and PER3, while CRY2 was down-regulated in both tumour and neighbouring tissue when compared to normal mucosa from unrelated donors." (PMID 27465361, 2016). "PER1 and CRY1 were both up-regulated in neighbouring and tumour tissue compared to normal mucosa, while PER2 and PER3 were up-regulated in neighbouring mucosa and down-regulated in the tumour tissue." (PMID 27465361, 2016). "Among the clock genes, the expression of PER1, PER2, PER3 and CRY2 were significantly elevated in the benign tissue compared to the tumour tissue (p = 0.001, 0.002, 0.037 and 0.001 respectively)." (PMID 27465361, 2016). "The targeted phase activation in the core CCG Per2 might serve as a potential target for therapies that might inhibit EMT, limit tumor metastasis, and minimize GSCs." (PMID 40495887, 2025). "Core circadian clock genes include the likely tumor suppressors PER1 and PER2 (53, –55)." (PMID 38319971, 2024). "In contrast, circadian regulators such as PER2 and PER3 generally act as tumour suppressors." (PMID 39566400, 2024). "PER2 is considered to be a tumor suppressor by inhibiting Epithelial-Mesenchymal Transition (EMT) and controlling cell proliferation; however, the ZnF704/SIN3A complex inhibits PER2 transcription, disrupts circadian rhythms, and exacerbates cancer cell invasion and metastasis." (PMID 39139571, 2024). "The specific phase activation in the Per2 gene is a potential target for treatments that may suppress EMT, minimize GSCs, and limit tumor metastasis." (PMID 36066207, 2022). "Given the circadian dysregulation in tumor cells, we investigated circadian rhythms in MDA-MB-231 and MDA-MB-468 cells by monitoring real-time bioluminescence from the introduced stable expression of the Bmal1::Luciferase and Per2::Luciferase (respectively)." (PMID 35440077, 2022). "However, PER2 and PER3 negatively correlate with tumor size, and TIM negatively correlates with tumor grade." (PMID 34697563, 2021). "Such dysregulation could alter PER2-SUMO conjugation and subsequently inhibit PER2 tumor suppression function by either facilitating its degradation or inhibiting its nuclear entry." (PMID 34257372, 2021). "Especially Per2 and BMAL1 genes have been more pronounced as tumor suppressors." (PMID 35126099, 2021). "Our results show that Per2, but not Per1, plays an important role in the stromal regulation of tumor progression." (PMID 33123539, 2020). "Meanwhile, others clock genes were downregulated including PER1 in 11 cancer types, PER2 in 7, PER3 and CRY2 in 10 and RORα in 11, indicating they may act as tumor suppressor genes." (PMID 33042011, 2020).
tumor (continued). "As an important core gene of the circadian clock, expression of Per2 is absent or decreased from tumor cells." (PMID 33083827, 2020). "A negative correlation between miR-34a expression and PER2 expression in tumour tissue was confirmed after cohort clustering." (PMID 31658284, 2019). "Separately, PER2 has been found to interact with HIF-1α and enhance HIF-1 activity, further demonstrating how circadian proteins can modulate the hypoxic response and therefore alter tumor behavior." (PMID 33089179, 2019). "Per2 and BMAL1 lose the ability of inhibiting tumor progression and hence promotes lung cancer." (PMID 29607311, 2018). "Previous studies have identified PER1 and PER2, components of the negative arm of the molecular clock, as tumour suppressor genes." (PMID 30348208, 2018). "PER1, PER2, PER3, CRY2 were found to be significantly down-expressed, while CLOCK, TIMELESS were over-expressed in the studied tumor samples compared to the non-tumor samples." (PMID 29958276, 2018). "PER1, PER2 and PER3 were lower in the tumour when compared to neighbouring benign mucosa." (PMID 27465361, 2016). "In the absence of PER2, Myc levels greatly rise, thereby explaining why many types of tumours display higher levels of CSNK1E than their normal cell equivalents." (PMID 27465361, 2016). "In these cells, the aspect of circadian deregulation was particularly evident, because Per2, a core oscillator gene with tumor suppressor function, was not expressed." (PMID 25310649, 2014). "In order to elucidate the interplay between the clock gene machinery and HCV replication, we decided to focus our attention on the role of PER2, as its role in regulating the daily rhythm of IFN-γ and its tumor suppressor activity have been already demonstrated." (PMID 23593233, 2013). "Paradoxically, other studies show that Per2-null mice are not tumor-prone, and Per2 and other clock genes may fuel tumorigenesis with a tumor-promoting function as similarly observed here for the role of PER2 in pituitary tumorigenesis." (PMID 37215573, 2023). "Regarding the negative elements of the clock machinery, Per2 genetic disruption accelerates tumor formation in different mouse models and overexpression of Per1 and Per2 genes sensitizes human cancer cells to apoptosis-mediated cell death induced by DNA damage." (PMID 34361055, 2021). "To test whether both genes are also essential for the stromal regulation of tumor progression, we injected MC38 cancer cells to the portal vein of mice in which each of the Per genes (Per1, Per2) was knocked-out separately, and assessed metastatic colonization." (PMID 33123539, 2020). "Expression of the tumor-promoting inflammatory factor IL-6, immunosuppressive factor PD1, and PD-L1 increased, whereas expression of the immune factor TNF-α and body rhythm-related factors Per1 and Per2 decreased in the night-shift group, and the difference was statistically significant." (PMID 33083827, 2020).